CCNYL1 (cyclin Y like 1)
Description:
Key regulator of Wnt signaling implicated in various biological processes including male fertility, embryonic neurogenesis and cortex development. Activates the cyclin-dependent kinase CDK16, and promotes sperm maturation.
Synonyms: FLJ40432
Tractability: Antibody: UniProt places it where antibodies can reach, with high confidence; its Gene Ontology location is reachable by antibodies, with high confidence; the Human Protein Atlas places it where antibodies can reach. PROTAC: ubiquitination databases record sites on it; its protein half-life has been measured.
Gene: Protein-coding gene on chromosome 2 (207,711,524 to 207,761,839, forward strand). Ensembl gene ENSG00000163249.
Subcellular location: Cell membrane
Subcellular location (Human Protein Atlas): Plasma membrane
Gene Ontology:
Molecular function: protein binding; cyclin-dependent protein serine/threonine kinase activator activity; protein kinase binding
Biological process: flagellated sperm motility; regulation of canonical Wnt signaling pathway; spermatogenesis
Cellular component: plasma membrane
Genetic constraint (gnomAD): Loss-of-function variants: 6 observed, 23.03 expected, observed/expected ratio (o/e) 0.26, 90% interval 0.14 to 0.51. The upper end of that interval is the gene's LOEUF score, 0.51, which puts it in group 2 of 6, group 1 being the genes least tolerant of losing a copy. Missense variants: 226 observed, 286.74 expected, observed/expected ratio (o/e) 0.79, 90% interval 0.71 to 0.88. Synonymous variants: 114 observed, 103.66 expected, observed/expected ratio (o/e) 1.1, 90% interval 0.94 to 1.28.
Homologues: Orthologues: chimpanzee CCNYL1 (100% identical), macaque CCNYL1 (99% identical), rat Ccnyl1 (96% identical), dog CCNYL1 (94% identical), pig CCNYL1 (94% identical), guinea pig CCNYL1 (93% identical), mouse Ccnyl1 (93% identical), rabbit CCNYL1 (82% identical), tropical clawed frog ccnyl1 (79% identical), zebrafish ccnyl1 (77% identical), Drosophila melanogaster CycY (60% identical), Caenorhabditis elegans cyy-1 (50% identical). Paralogues in human: CCNY (70% identical), CCNYL1B (47% identical).
Diseases named in the same sentence as CCNYL1 in open-access papers:
CCNYL1 is named in the same sentence as 9 diseases in open-access papers, as found by Europe PMC text mining. Sharing a sentence is not in itself a finding about the gene and the disease. The quoted sentences say what the papers report.
colon cancer (1 paper, 2021). "Whereas expression levels of CCNY, CCNYL1, and CDK16 were broadly comparable across all cell types, the average level of CDK14 was more than an order of magnitude lower in colon cancer cells compared to any other tissue included in this analysis." (PMID 34571979, 2021).
epididymitis (1 paper, 2021). Inflammation of the epididymis. "We found that Ccnyl1 expression was elevated; however, Sept4 and Krt1 were reduced in sperm from cauda epididymitis, indicating that the expression of flagella-related proteins was disturbed in Cabs1 KO mice." (PMID 33440775, 2021).
infertile (1 paper, 2015). "Using the Ccnyl1 knockout model, we found that male but not female Ccnyl1-/- mice were infertile, accompanied by sperm defects in both motility and structural integrity." (PMID 26305884, 2015).
prostate carcinoma (1 paper, 2014). A carcinoma that arises from epithelial cells of the prostate gland. "Furthermore, the four validated mirT RDDs in DDX58 and CCNYL1 resided in binding regions of miRNAs hsa-miR-10b, hsa-miR-98 and hsa-miR-122, which have all been reported to be dysregulated in prostate cancer relative to adjacent benign." (PMID 25036877, 2014). "CCNYL1 is a crucial regulator of cell cycle transitions, and is up-regulated in prostate cancer." (PMID 25036877, 2014).
CCNYL1 also shares sentences with these, for which no sentence is quoted: tumor (2 papers); asthenozoospermia (1); infection (1); male infertility (1); mastitis (1).